GNMT (glycine N-methyltransferase)
Diseases named in the same sentence as GNMT in open-access papers (continued):
Sharing a sentence is not in itself a finding about the gene and the disease.
liver fibrosis (11 papers, 2018 to 2026). "Understanding the mechanism underlying GNMT repression is essential for the development of new therapeutic approaches in liver fibrosis and cholestatic diseases." (PMID 30237481, 2018). "The inverse association between GNMT and miR-873-5p expression was confirmed in different preclinical models of liver fibrosis." (PMID 30237481, 2018). "To date, little is known about the mechanisms underlying downregulation of GNMT levels in hepatic fibrosis and cirrhosis." (PMID 30237481, 2018). "In this study, we show that liver fibrosis progression is associated with the repression of GNMT, which is targeted by miR-873-5p in two preclinical models of liver fibrosis and cholestasis: the bile duct ligation (BDL) and the Mdr2 (Abcb4)-deficient mice (Mdr2-/-), respectively." (PMID 30237481, 2018). "Sarcosine is involved in hepatic S-adenosylmethionine homeostasis as a methylation product of glycine mediated by glycine N-methyltransferase (GNMT), and its deletion results in the development of steatotic liver fibrosis in mice." (PMID 40100312, 2025). "On the other hand, the glycine-N-methyltransferase (GNMT) was reported to be downregulated in HCC and its genetic deficiency was shown to trigger DNA hypermethylation, liver fibrosis, and cancer in mice." (PMID 34680398, 2021). "In this work, we aim to study the regulation of GNMT by microRNAs during liver fibrosis and cirrhosis." (PMID 30237481, 2018). "The down-regulation of GNMT can be through the DNA methylation of its promoter region and microRNA-mediated post-transcriptional regulation in disease models and clinical studies, liver fibrosis and cirrhosis, and HCC." (PMID 31470507, 2019). "Thus, the expression of α-smooth muscle actin (α-SMA), a typical marker of activated HSCs32, was assessed to evaluate the effect of hepatic AAV8-mediated GNMT on HSC activation during hepatic fibrosis." (PMID 30217986, 2018). "Thus, we conclude that there is infiltration of macrophages to clear apoptotic cell debris and that MMP‐12 expression may be important mediators of hepatic fibrosis in GNMT‐/‐ mice." (PMID 32951289, 2020). "Summing up, the significant inverse correlation between hepatic GNMT and miR-873-5p expression both in cirrhotic and cholestatic patients targeting the miR-873-5p/GNMT axis may provide a novel therapeutic approach to treat liver fibrosis." (PMID 30237481, 2018). "SPP1, GNMT, CLDN11, and THBS2 were determined in the transformation process of MASH to liver fibrosis." (PMID 38726780, 2025). "Four genes (SPP1, GNMT, CLDN11, and THBS2) were the intersection genes with the potential to affect the transformation process of MASH to liver fibrosis." (PMID 38726780, 2025). "In this study, we utilized four public GEO datasets to obtain four genes (SPP1, GNMT, CLDN11, and THBS2) affecting the transformation of MASH to hepatic fibrosis." (PMID 38726780, 2025). "Therefore, we conclude that reduced AhR signaling is at least partially responsible for the lack of immune signaling, and hence, accumulation of hepatic fibrosis in GNMT‐/‐ mice." (PMID 32951289, 2020). "We hypothesized that lipotoxicity would not be a major factor in GNMT‐/‐ mouse liver fibrosis since there is abundant PC synthesis that would prevent toxic lipid accumulation." (PMID 32951289, 2020). "In addition, AAV8-GNMT ameliorated CCl4-induced liver fibrosis, suggesting that AAV8-mediated GNMT intervention may have beneficial effects on chronic liver diseases." (PMID 30217986, 2018). "Finally, the HFD did not significantly influence the level of hepatic fibrosis in GNMT‐/‐ mice." (PMID 32951289, 2020).
Cirrhosis (8 papers, 2018 to 2021). A chronic disorder of the liver in which liver tissue becomes scarred and is partially replaced by regenerative nodules and fibrotic tissue resulting in loss of liver function. "Correlation between GNMT and miR-873-5p in human cholestasis and cirrhosis together with miR-873-5p inhibition in vivo in different mouse models of liver cholestasis and fibrosis [bile duct ligation and Mdr2 (Abcb4)-/- mouse] were then assessed." (PMID 30237481, 2018). "A decrease in GNMT levels occurs in NAFLD, at early stages of fibrosis, cirrhosis, and HCC1,6,7,34,35." (PMID 30237481, 2018). "Glycine N-methyltransferase (GNMT), the main gene involved in liver S-adenosylmethionine (SAM) catabolism, is down-regulated in the liver of HFD hamsters, as well as patients with cirrhosis and HCC." (PMID 34680557, 2021). "Furthermore, in the clinical setting, we have found high levels of circulating miR-873-5p in the serum of cirrhotic patients as well as a negative correlation between hepatic GNMT and miR-873-5p in human cirrhosis and cholestasis." (PMID 30237481, 2018).
hypermethioninemia (5 papers, 2015 to 2022). "Hypermethioninemia is caused by the deficiency of glycine N-methyltransferase (GNMT) activity and/or mutations of the MAT1A gene, which resulted in the plasma concentration of methionine reaching as high as 1870 μM (normal range 5–35 μM)." (PMID 32528425, 2020). "In the differential diagnosis of hypermethioninemia also deficiencies of S-adenosylhomocysteine hydrolase, adenosine kinase and glycine N-methyltransferase need to be mentioned." (PMID 26289392, 2015). "Further causes of hypermethioninemia include IEM of Met, S-adenosylmethionine and S-adenosylhomocysteine, such as deficiencies of Met adenosyltransferase I and III (MAT I/III), glycine N-methyltransferase (GNMT), and s-adenosylhomocysteine (AdoHcy) hydrolase, and citrin deficiency." (PMID 34449519, 2021).
Obesity (5 papers, 2020 to 2025). Accumulation of substantial excess body fat. "Key genes within locus 6.52, including VEGFA, SRF, and GNMT, established a link between obesity and chronic ischemic heart disease." (PMID 40565603, 2025). "Instead, we found that the GNMT‐/‐ mice were resistant to HFD‐induced obesity that we observed in the GNMT‐/‐ mice." (PMID 32951289, 2020).
prostate tumors (5 papers, 2013 to 2022). "Using this knowledge as an example or a positive control, we investigated whether “Glycine-N-methyltransferase” (D050938) and “One-carbon group transferases” (D019875) could be obtained when “Sarcosine” (D012521) and “Prostate neoplasm” (D011471) were used as queries." (PMID 35208208, 2022).
atherosclerosis (4 papers, 2014 to 2023). A disease characterized by the build-up of fatty material and calcium deposition in the arterial wall resulting in partial or complete occlusion of the arterial lumen. "Additionally, it is known that global hypomethylation is seen in atherosclerosis, and we suspect that variation in GNMT could affect risk status." (PMID 24651765, 2014). "Our previous studies demonstrated that the expression of GNMT was increased in atherosclerosis and dextran sulfate sodium (DSS)-induced colitis." (PMID 37047834, 2023). "Our previous study revealed that deletion of GNMT exacerbates the consequences of atherosclerosis and ulcerative colitis, implying that GNMT expression is important in inflammatory diseases." (PMID 37047834, 2023). "Deletion of GNMT exacerbated the inflammatory response in atherosclerosis and DSS-induced colitis." (PMID 37047834, 2023).
glycogen storage disease (4 papers, 2014 to 2020). "Furthermore, mice that lack the enzyme glycine N-methyltransferase (GNMT), which regulates the ratio of SAM to S-adenosylhomocysteine (SAH), develop glycogen storage disease in the liver." (PMID 32257815, 2020).
Insulin resistance (4 papers, 2016 to 2020). Increased resistance towards insulin, that is, diminished effectiveness of insulin in reducing blood glucose levels. "In agreement with the previous study, our results showed upregulated NNMT, which correlates positively with insulin resistance, and downregulated GNMT, deficiency of which is known to impair glucose tolerance and insulin sensitivity." (PMID 32518576, 2020). "To investigate whether GNMT deficiency contributes to the metabolic phenotype arising from glucose intolerance and insulin resistance, we applied a glucose tolerance test and an insulin tolerance test to a Gnmt−/− mouse model." (PMID 27716281, 2016). "We demonstrated that hepatic GNMT regulated lipid and glucose homeostasis, and provided insight into the development of insulin resistance by modulating the PI3K/Akt pathway." (PMID 30115977, 2018). "And the overexpression of GNMT provides insight into the development of insulin resistance through the modulation of the PI3K/Akt pathway." (PMID 30061177, 2018). "Our data indicate that hepatic GNMT regulates lipid and glucose homeostasis, and provide insight into the development of insulin resistance through modulating the PI3K/Akt pathway." (PMID 27716281, 2016).
pancreatic cancer (4 papers, 2019 to 2023). "In this study, we analyzed the expression of GNMT in a panel of pancreatic cancer cell lines and in early-stage paired patient tissue samples (normal and diseased) by quantitative reverse transcription-PCR (qRT-PCR)." (PMID 33802396, 2021). "We looked at the expression levels of GNMT in a panel of seven pancreatic cancer cell lines, and confirmed that GNMT is significantly downregulated in a majority of these cell lines." (PMID 33802396, 2021). "In this study, we have determined the expression level of GNMT in a panel of seven pancreatic cancer cell lines, and seven high-quality paired early-stage tumor tissue from PC patients." (PMID 33802396, 2021). "The protein products from AGR2, CEAMAN6, GNMT, PDIA2, POSTN, RBPJL and S100P have been reported as potential diagnostic and prognostic biomarkers for pancreatic cancer or have demonstrated to be involved in either pancreatic cancer, initiation, migration, invasion, metastasis, or chemoresistance." (PMID 36812168, 2023). "Our data also shows down regulation of tumour suppressor genes AZGP1, EGLN1 and GNMT of which AZGP1, a Zinc α2-glycoprotein which when silenced was shown to increase invasiveness of pancreatic cancer by induction of mesenchymal transition." (PMID 35854233, 2022). "The analytic results demonstrated that 7 upregulated (MMP9, CXCL8, ACTB, ITGB1, STAT1, TOP2A and CDK1) and 2 downregulated (GNMT and ABAT) hub genes may act as the key genes in pancreatic cancer." (PMID 31061236, 2019). "Using this approach and verifying the data using individual gene expression data, we found that AGR2, CEACAM6, GNMT, PDIA2, POSTN, RBPJL, and S100P are upregulated in pancreatic tumor tissue as compared to non-tumor tissue from Black and White patients." (PMID 36812168, 2023).
breast carcinoma (2 papers, 2014 to 2021). "Expressions of sarcosine metabolism-related proteins including GNMT varied according to subtype of breast cancer." (PMID 34065390, 2021). "Expression of sarcosine metabolism-related proteins differed significantly according to breast cancer subtype (GNMT, p = 0.005; SARDH, p = 0.012; tumoral PIPOX, p = 0.008; stromal PIPOX, p < 0.001)." (PMID 24884785, 2014). "The GNMT and MAT1A protein expressions and the C/N ratio of MAT2A were also correlated with the five-year relative survival rate in our breast cancer cohort." (PMID 34065390, 2021). "GNMT, MAT1A, MAT2A-biomarker IHC panel was compared with the clinical survival record in breast cancer patients, to examine the accuracy of IHC-based methods for identifying clinical prognosis." (PMID 34065390, 2021). "We analyzed the expression of GNMT, SARDH, and PIPOX in a tissue microarray of 721 breast cancer cases using immunohistochemistry (IHC)." (PMID 24884785, 2014). "Although we did not measure sarcosine levels directly from breast cancer tissues, we used expression levels of the major sarcosine metabolism-related proteins GNMT, SARDH, and PIPOX as surrogate for sarcosine level." (PMID 24884785, 2014). "Moreover, analysis of sarcosine metabolism phenotype revealed that patients with sarcosine-high type [GNMT(+)/SARDH and PIPOX(-)] tumors had a shorter DFS than patients with other breast cancer tumor types, suggesting that sarcosine level is a prognostic factor in breast cancer." (PMID 24884785, 2014). "mRNA expression of GNMT and MAT1A was not related to breast cancer survival." (PMID 34065390, 2021).
breast tumor (2 papers, 2019 to 2021). "Noteworthy, it has been found that human epidermal growth factor‐2 (HER‐2)‐positive breast tumours display upregulation of sarcosine metabolism‐related enzymes (GNMT, SARDH, PIPOX)." (PMID 30628163, 2019). "We examined the specimens from 252 independent patients and compared the subcellular protein expression of GNMT, MAT1A, and MAT2A between the breast tumor and their paired normal breast tissues by Immunohistochemistry (IHC) analysis." (PMID 34065390, 2021). "IHC analysis revealed that GNMT was downregulated in breast tumor tissues compared with normal breast tissues (p = 0.004)." (PMID 34065390, 2021). "GNMT was downregulated in breast tumor tissues compared with normal breast tissues." (PMID 34065390, 2021).
cholestasis (2 papers, 2018 to 2020). Impairment of the bile flow caused by obstruction within the liver, or outside the liver in the bile duct system. "Moreover, GNMT deficiency aggravates cholestasis-induced fibrogenesis." (PMID 30237481, 2018).
diabetes (2 papers, 2016 to 2020). "We previously demonstrated that hepatic GNMT is decreased in high-fat-diet-induced type 2 diabetes mellitus, but its contribution to metabolic syndrome is unclear." (PMID 27716281, 2016). "We further confirmed that carnosine treatment increased the GNMT activity in diabetes mice." (PMID 33241846, 2020).
glioma (2 papers, 2022 to 2025). A benign or malignant brain and spinal cord tumor that arises from glial cells (astrocytes, oligodendrocytes, ependymal cells). "In vitro experiments have shown that glioma cells convert glycine to sarcosine through glycine-N-methyltransferase, leading to elevated sarcosine levels in the microenvironment." (PMID 40406272, 2025). "Our study suggested the protective effects of GNMT in glioma, inspiring further research on it." (PMID 36467068, 2022).
hyperhomocysteinemia (2 papers, 2014 to 2022). A serious metabolic condition caused by mutations in the MTHFR gene, medications, or nutritional deficiency. "Further, hyperhomocysteinemia is a risk factor for stroke and cardiovascular disease, and these data indicate GNMT may represent a new pharmacogenetic target for reducing stroke risk." (PMID 24651765, 2014). "Such mtDNA hypermethylation in PCOS may be linked to hyperhomocysteinemia and subsequent significant upregulation of the one-carbon metabolic enzymes betaine homocysteine methyltransferase (BHMT) and glycine N-methyltransferase (GNMT) and the DNA methyltransferase DNMT1." (PMID 36498989, 2022).
hyperlipidemia (2 papers, 2020 to 2021). "In this line, a study with glycine n-methyltransferase-deficient mice (glycine n-methyltransferase participates in the catabolism of betaine to glycine) showed that these deficient mice developed hyperlipidemia and steatohepatitis." (PMID 34684533, 2021).
metabolic syndrome (2 papers, 2016 to 2019). A cluster of metabolic risk factors for CARDIOVASCULAR DISEASES and TYPE 2 DIABETES MELLITUS. "Our data suggested that the GNMT may function as a negative regulator for Angptl8 expression in metabolic syndrome." (PMID 31470507, 2019). "Here we show that GNMT modulates key aspects of metabolic syndrome in mice." (PMID 27716281, 2016). "In conclusion, our study suggests that downregulation of hepatic GNMT and upregulation of hepatic and circulating Angptl8 may be a potential biomarker for HFD-induced metabolic syndrome." (PMID 31470507, 2019).
Nephropathy (2 papers, 2018 to 2020). A nonspecific term referring to disease or damage of the kidneys. "Here, we aim to delineate the role of GNMT in AAI-induced nephropathy and clarify the molecular mechanism underlying its action." (PMID 29725048, 2018). "Another study, by Chang and colleagues, reported that G lycine N-methyltransferase (GNMT) exerted protective effects against AA-induced nephropathy in female mouse hepatocytes by reducing NQO1 expression and increasing CYP3A44 expression." (PMID 32050524, 2020). "Our findings suggest that CYP3A44/3A41 regulated by GNMT is highly related to reduced AAI nephropathy in mice, although the catalytic activities of mouse CYP3A44/CYP3A41 towards AAI have never been reported." (PMID 29725048, 2018). "In summary, hepatic GNMT protected mice from AAI nephropathy by enhancing CAR/PXR/CYP3A44/3A41 transcriptions and reducing Nrf2/NQO1 transcriptions." (PMID 29725048, 2018). "To confirm the role of hepatic GNMT in AAI-induced nephropathy, we performed adeno-associated virus (AAV)-based gene therapy to restore GNMT protein in the liver of KO mice and observed the protective ability of GNMT." (PMID 29725048, 2018). "This study aims to determine the role of GNMT in AA-induced nephropathy." (PMID 29725048, 2018). "Microarray analysis and AAI-treated mouse models showed that GNMT moderately reduced AAI-induced nephropathy by lowering the upregulated level of NQO1 in male, but significantly improved the nephropathy additionally by increasing Cyp3A44/3A41 in female." (PMID 29725048, 2018). "Interestingly, in male GNMT Tg mice with severe kidney damage, GNMT-CAR and GNMT-PXR levels slightly increased, but were still lower than that of GNMT-Nrf2." (PMID 29725048, 2018). "However, in male mice, absence of Cyp3A44/3A41was related to the AAI intolerance, even in the GNMT Tg mice, the AAI-induced nephropathy was barely decreased." (PMID 29725048, 2018). "The protective effects of GNMT were absent in female GNMT knockout mice, in which re-expression of hepatic GNMT significantly decreased AAI-induced nephropathy." (PMID 29725048, 2018).
Non-Alcoholic Fatty Liver Disease (2 papers, 2019 to 2022). "Indeed, the increase of hepatic SAM and the decrease of hepatic GNMT were linked to non-alcoholic fatty liver disease in a HFD-fed rodent model." (PMID 31470507, 2019). "Accumulation of SAM and downregulation of GNMT are frequently found in rodent models of HFD-induced nonalcoholic fatty liver disease." (PMID 31470507, 2019).
polycystic ovaries (2 papers, 2016 to 2024). "Another study found that gilt polycystic ovaries were associated with a high homocysteine concentration in follicular fluid and the up-regulation of betaine homocysteine methyltransferase and glycine N-methyltransferase enzymes, both involved in one-carbon metabolism." (PMID 39449362, 2024).
Sepsis (2 papers, 2022 to 2025). Sepsis is defined as life-threatening organ dysfunction caused by a dysregulated host response to infection. "Given that sepsis dysregulates glycine metabolism in mice, we examined whether DCA might blunt glycine deficiency during sepsis by assessing GNMT, SARDH, SHMT1, and SHMT2, the key enzymes involved in glycine metabolism." (PMID 35730570, 2022). "The relative expression levels of GNMT, SEMA4B, FURIN, and RNASE2 were significantly lower in the sepsis group than those in the control group." (PMID 40526611, 2025).
type II diabetes (2 papers, 2016 to 2022). "This is further supported by our findings of reduced GNMT expression in NASH and type II diabetes patients." (PMID 35216100, 2022).
bladder cancer (1 paper, 2023). "Immunostaining of 86 human bladder cancer cases showed that GNMT expression was higher in cases with muscle invasion and metastasis." (PMID 38003554, 2023).
chronic kidney disease (1 paper, 2020). Impairment of the renal function secondary to chronic kidney damage persisting for three or more months. "The role of GNMT in chronic kidney disease such as DKD has never been reported previously." (PMID 33241846, 2020).
co-infection (1 paper, 2018). "Thus, the significant decline of GNMT in a stage-specific fashion by mono- and co-infection suggests that GNMT plays a key role in acceleration of progression of HCC." (PMID 30138348, 2018).